IGHG1 (immunoglobulin heavy constant gamma 1 (G1m marker))
Diseases named in the same sentence as IGHG1 in open-access papers (continued):
Sharing a sentence is not in itself a finding about the gene and the disease.
breast carcinoma (continued). "Through detecting the expression of both Igγ and IGHG1 mRNA in the same breast cancer cells using ISH and IHC on serial sections we confirmed that Igγ expression in breast cancer cells was the result of production of IgG by these cells." (PMID 23554916, 2013). "The number of IGHG1 mRNA expressing breast cancer cells is much larger than that of Igγ expressing ones." (PMID 23554916, 2013). "By performing ISH with an IGHG1 antisense probe, we identified IGHG1 mRNA expression in breast cancer cells." (PMID 23554916, 2013). "Athymic nude mice were used to investigate the in vivo effects of IGHG1 on breast cancer cells." (PMID 36883223, 2023). "Together, these data confirmed a key role for IGHG1 during breast cancer cell progression." (PMID 36883223, 2023). "In this study, we used a range of molecular and cell-based assays to show that increased expression of IGHG1 in breast cancer cells activates AKT and vascular endothelial growth factor (VEGF) signaling, leading to enhanced cell proliferation, invasion, and angiogenesis." (PMID 36883223, 2023). "qRT-PCR and western blot analysis of four breast cancer cell lines MCF-7, MDA-MB-231, T47D, and BT-549 revealed considerably higher IGHG1 mRNA and protein expression compared to the normal epithelial cell line MCF-10A." (PMID 36883223, 2023). "Conversely, other reports describe IGHG1 and IGHG3 as suppressor genes in breast cancer recurrence." (PMID 41149858, 2025). "Furthermore, in order to confirm that positive Igγ expression was actually the result of Igγ production by these breast cancer cells, ISH with an antisense probe to IGHG1 was performed on serial sections." (PMID 23554916, 2013).
gastric cancer (5 papers, 2021 to 2023). A primary or metastatic malignant neoplasm involving the stomach. "In order to understand the detailed molecular mechanism of β-Catenin activation modulated by IGHG1, we further performed linear association study on β-Catenin and IGHG1 mRNA and protein levels among clinical samples from gastric cancer patients." (PMID 34315496, 2021). "Our study provided novel clues for the role of IGHG1 in gastric cancer oncogenesis, and enlightened future exploration for targeted therapy development." (PMID 34315496, 2021). "Immunohistochemical staining method was used to detect the expression of IGHG1 protein in gastric cancer tissues." (PMID 33995624, 2021). "We found that IGHG1 is highly expressed in gastric cancer tissues compared with normal control tissues." (PMID 33995624, 2021). "And we also further delineated the regulatory role of IGHG1 on Wnt/β-Catenin pathway, in order to identify potential target for future gastric cancer treatment." (PMID 34315496, 2021). "The molecular mechanism of IGHG1 affecting EMT in gastric cancer SGC7901 cells was preliminarily confirmed, which provided experimental and theoretical basis for elucidating the molecular mechanism of gastric cancer." (PMID 33995624, 2021). "This study provided novel evidences that IGHG1 acted as oncogene by promotion of gastric cancer cellular proliferation, migration and chemo-resistance." (PMID 34315496, 2021). "IGHG1 promoted gastric cancer cell proliferation, invasion and chemo-resistance through up-regulation of β-Catenin level mediated by Akt/GSK-3β phosphorylation." (PMID 34315496, 2021). "We then detected IGHG1 protein expression in several gastric cancer and normal epithelial cell lines." (PMID 34315496, 2021). "As a result, GEP profiling data of gastric cancer tissue exhibited significantly elevated IGHG1 mRNA level compared with normal tissues (p < 0.05)." (PMID 34315496, 2021). "And IGHG1 acted as important regulator in gastric cancer cell proliferation, metastasis and chemo-resistance." (PMID 34315496, 2021). "Next, we examined the expression of IGHG1 protein in gastric cancer SGC7901, MGC803, BGC823 cells and immortalized gastric mucosal epithelial GES-1 cells by western blot." (PMID 33995624, 2021). "According to iTRAQ technology and 2D LCMS/MS, 243 differentially expressed proteins related to gastric cancer were preliminarily screened and identified, including IGHG1." (PMID 33995624, 2021). "The results from our study demonstrated that IGHG1 upregulation in gastric cancer significantly elevated Akt and GSK-3β phosphorylation, which in turn increased β-Catenin level by suppression its degradation caused by phosphorylation." (PMID 34315496, 2021). "Functional study further demonstrated that IGHG1 promoted proliferative and migration as well as chemo-resistance of gastric cancer tumor cells." (PMID 34315496, 2021). "Firstly, the expression of IGHG1 protein in gastric cancer tissue chips (including 90 patients with gastric cancer) was detected by immunohistochemistry." (PMID 33995624, 2021). "Based on previous studies, we found that IGHG1 was highly expressed in gastric cancer, participated in the proliferation, migration and invasion of SGC7901 cells and affects EMT of SGC7901 cells." (PMID 33995624, 2021). "Our study provided novel clues in β-Catenin activation triggered by IGHG1 in gastric cancer pathogenesis, which emphasized the potential therapeutic value in targeting β-Catenin in gastric cancer treatment." (PMID 34315496, 2021). "IGHG1 is a differentially expressed protein screened out in gastric cancer in the early stage of the subject group." (PMID 33995624, 2021). "Our research further suggested that IGHG1/AKT/GSK-3β/β-Catenin axis acted as novel pathway which regulated gastric cancer cellular malignant behavior." (PMID 34315496, 2021). "In this study, we demonstrated for the first time that IGHG1 upregulation was important feature of gastric cancer patients." (PMID 34315496, 2021).
gastric cancer (continued). "IGHG1 overexpression has also been reported for the induction of epithelial to mesenchymal cell transmission (EMT) in gastric cancer via tumor growth factor beta (TGF-β)/SMAD3 signaling, whilst AKT/glycogen synthase kinase 3 beta (GSK-3β)/β-catenin pathway is also highly active." (PMID 36883223, 2023). "Gastric cancer tissues and tumor cell lines demonstrated significantly higher level of IGHG1." (PMID 34315496, 2021). "IGHG1 promotes the proliferation, migration and invasion of gastric cancer cells." (PMID 33995624, 2021). "Western blot was used to detect the expression of IGHG1 in gastric cancer cells." (PMID 33995624, 2021). "In order to explore the role of IGHG1 on gastric cancer cells." (PMID 34315496, 2021). "Our study provided consistent results that IGHG1 significantly promoted proliferative and migrative capabilities of gastric cancer cells, which could be potential therapeutic target in future treatment development." (PMID 34315496, 2021). "In this study, we demonstrated that IGHG1 upregulation was characteristic in gastric cancer cells." (PMID 34315496, 2021). "In addition, it was reported that IGHG1 could induce EMT in gastric cancer cells by regulating TGF-β/SMAD3 signaling pathway, which is in line with our study." (PMID 34315496, 2021). "Moreover, subsequent western blot assay on four pairs of gastric cancer and normal tissue samples as well as qRT-PCR study on clinical gastric cancer samples in our clinical center also suggested that IGHG1 protein and mRNA level were significantly elevated in cancer tissues (p < 0.001)." (PMID 34315496, 2021). "In our experiments, the expression of EMT signaling pathway protein TGF-β was decreased in SGC7901 cells when IGHG1 was poorly expressed, indicating that IGHG1 may promote the migration and invasion of gastric cancer cells through the TGF-β/SMAD signaling pathway." (PMID 33995624, 2021). "Further experiments indicated that IGHG1 activated AKT/GSK-3/-Catenin axis, which played crucial role in regulation of proliferative and chemo-resistance of gastric cancer cells." (PMID 34315496, 2021). "This topic explores the expression of IGHG1 in gastric cancer and the effect of IGHG1 on the proliferation, migration, invasion and EMT of gastric cancer SGC7901 cells and its mechanism of action." (PMID 33995624, 2021). "To further investigate the role of IGHG1 in tumor cell migrative capabilities of gastric cancer patients, we performed wound healing assay on MKN45 and AGS cancer cell groups respectively transfected with IGHG1 overexpression and IGHG specific shRNA vectors." (PMID 34315496, 2021). "In gastric cancer, AKT/GSK-3β/β-catenin signaling is upregulated in IGHG1 cells." (PMID 36883223, 2023). "Surgical tissues and gastric cancer cell lines were retrieved to evaluate IGHG1 expression for patients with or without lymph node/distal organ metastasis." (PMID 34315496, 2021).
colorectal cancer (4 papers, 2021 to 2025). A primary or metastatic malignant neoplasm that affects the colon or rectum. "The IGHG1 glycopeptides identified as #5, #6, #11, and #14 in our study were also detected in the serum of colorectal cancer patients and healthy controls." (PMID 40890283, 2025). "Data from qRT-PCR and western blot analysis showed that IGHG1 was up-regulated in the colorectal cancer cells." (PMID 34553073, 2021). "In summary, IGHG1, up-regulated in the colorectal cancer tissues and cells, contributed to the proliferation of colorectal cancer cells through increasing heme biosynthesis and decreasing PpIX accumulation." (PMID 34553073, 2021). "Results demonstrated that shRNA-mediated down-regulation of IGHG1 decreased cell viability of colorectal cancer and suppressed cell proliferation." (PMID 34553073, 2021). "Considering IGHG1 was involved in the tumorigenesis of a variety of cancers, the functional role of IGHG1 in colorectal cancer was investigated in this study." (PMID 34553073, 2021). "Knockdown of IGHG1 decreased the cell viability of colorectal cancer and suppressed cell proliferation." (PMID 34553073, 2021). "Knockdown of IGHG1 inhibited the cell viability and proliferation of HT29 cells, demonstrating that silence of IGHG1 had an anti-proliferative effect on colorectal cancer cells." (PMID 34553073, 2021). "HT29 was transfected with shRNA targeting IGHG1 to investigate the functional role of IGHG1 in colorectal cancer." (PMID 34553073, 2021). "Colorectal cancer cells were then transfected with shRNA targeting IGHG1 to down-regulate IGHG1 and conducted with Cell Counting Kit 8 (CCK8) and colony formation assays." (PMID 34553073, 2021). "Compared with control, cells transfected with shIGHG1 showed higher intensity of cellular fluorescence of PpIX, indicating that knockdown of IGHG1 enhanced PpIX accumulation in the colorectal cancer cell." (PMID 34553073, 2021). "In prostate and colorectal cancer, MEK/ERK/c-Myc signaling is associated with IGHG1 overexpression." (PMID 36883223, 2023). "In colorectal cancer, the upregulation of IGHG1 contributes to increased cellular proliferation." (PMID 36883223, 2023). "However, the in-vivo regulatory role of IGHG1 in colorectal cancer should be further investigated to confirm the anti-tumor effect of IGHG1 silence." (PMID 34553073, 2021). "Moreover, the effect of IGHG1 on colorectal cancer cell migration and invasion will be investigated in further research." (PMID 34553073, 2021). "In addition, phosphorylated ERK was also decreased by knockdown of IGHG1 in HT29 cells, showing that silence of IGHG1 retarded MEK-FECH signaling transduction in colorectal cancer." (PMID 34553073, 2021). "IGHG1 was found to be enhanced in the colorectal cancer cells." (PMID 34553073, 2021). "Higher expression of IGHG1 was identified in the colorectal cancer cells (HT29, SW480, SW620, and HCT116) compared to human intestinal epithelial cell (HIEC), suggesting that IGHG1 might be implicated in colorectal cancer progression." (PMID 34553073, 2021). "Moreover, heme content in HT29 cells was reduced by knockdown of IGHG1, revealing that knockdown of IGHG1 suppressed heme biosynthesis in the colorectal cancer cell." (PMID 34553073, 2021). "In the MEK-FECH axis-dependent pathway, suggesting that IGHG1 might be a novel potential therapeutic target for colorectal cancer treatment." (PMID 34553073, 2021). "IGHG1 was hypothesized to regulate PpIX accumulation and heme biosynthesis during the development of colorectal cancer in this study." (PMID 34553073, 2021). "Additionally, a recent study revealed that individuals with colorectal cancer may have changes in their tumor immune microenvironment due to an Asia-specific variation of the IGHG1 gene." (PMID 36941725, 2023).
colorectal cancer (continued). "In the present study, cellular fluorescence of PpIX was enhanced by knockdown of IGHG1 in the colorectal cancer cells, indicating that IGHG1 might be a potential therapeutic target for the treatment of colorectal cancer through regulation of PpIX accumulation and heme biosynthesis." (PMID 34553073, 2021). "Therefore, IGHG1 might be involved in colorectal cancer progression." (PMID 34553073, 2021). "Knockdown of IGHG1 reduced the expression and the activity of FECH protein, an enzyme involved in heme biosynthesis, in HT29 cells, which indicated that IGHG1 contributed to FECH activation in colorectal cancer." (PMID 34553073, 2021). "However, the roles of IGHG1 in the colorectal cancer cell proliferation and PpIX accumulation have not been reported yet." (PMID 34553073, 2021).
glioma (4 papers, 2011 to 2023). A benign or malignant brain and spinal cord tumor that arises from glial cells (astrocytes, oligodendrocytes, ependymal cells). "In our study, we firstly analyzed the expression of IGHG1, the gene encoding the heavy chain of IgG, in glioma with bioinformatics methods." (PMID 34760705, 2021). "From the results, we drew the conclusion that the expression of IGHG1 is upregulated in patients with glioma." (PMID 34760705, 2021). "In this study, we found that the expression of IGHG1 was higher in glioma and molecular subtypes with poor prognosis." (PMID 34760705, 2021). "To summarize, the same with ssGSEA, GO and KEGG analyses revealed that IGHG1 plays a role in immune-related processes in glioma." (PMID 34760705, 2021). "The expression level of IGHG1 in patients with glioma was apparently upregulated from the GEO and TCGA databases, especially in GBM." (PMID 34760705, 2021). "In this study, we firstly analyzed the expression of IGHG1 in glioma and its relationship with prognosis through The Cancer Genome Atlas (TCGA), Gene Expression Omnibus (GEO), and the Chinese Glioma Genome Atlas (CGGA) databases." (PMID 34760705, 2021). "In this study, we found that the expressions of IGHG1/cancer-IgG were higher in glioma with poor prognosis." (PMID 34760705, 2021). "Stratification analysis was programmed to evaluate the influence of IGHG1 expression on the prognosis of glioma patients." (PMID 34760705, 2021). "Together, IGHG1/cancer-IgG are promising biomarkers of diagnosis and treatment in patients with glioma." (PMID 34760705, 2021). "We found that the expression of IGHG1 in patients with glioma was higher than that in normal tissues from the GEO database (p < 0.01)." (PMID 34760705, 2021). "We mined open databases including the Chinese Glioma Genome Atlas (CGGA), The Cancer Genome Atlas (TCGA), and the Gene Expression Omnibus (GEO) to study the role of IGHG1, which encodes cancer-IgG in glioma." (PMID 34760705, 2021). "Among these 4 proteins, SNX1 and IGHG1 were up-regulated in gliomas, while, PQBP1 and EYA1 were down-regulated in gliomas." (PMID 26370624, 2015). "In order to further verify the role of IGHG1 in glioma, we performed stratified analysis." (PMID 34760705, 2021). "In our study, we explored the role of IGHG1 in the glioma microenvironment with ssGSEA." (PMID 34760705, 2021). "A high expression of IGHG1 indicates more immune cell infiltration in glioma (p < 0.001)." (PMID 34760705, 2021). "In addition, IGHG1/cancer-IgG were closely related to immune cell infiltration in the glioma microenvironment." (PMID 34760705, 2021). "However, there were no common proteins which were differentially expressed in Grade II and IV with the exception of 4 proteins, SNX1, EYA1, PQBP1, and IGHG1, which were dysregulated across all the grades of gliomas." (PMID 26370624, 2015). "The most extreme cohort-independent changes in overall survival were observed in Ighg1 (HR = 4.33) and Tgfa (HR = 0.12), and the former trend has been found in cancer cell lines; meanwhile the later is present in the KEGG glioma pathway." (PMID 21649900, 2011). "However, cancer-IgG and IGHG1 have not been studied in gliomas." (PMID 34760705, 2021).
myeloma (3 papers, 2024 to 2025). "C2 IGHG1+ Myeloma cells were enriched in cytoplasmic translation, ribosome biogenesis, ribonucleoprotein complex biogenesis, ribosomal small subunit biogenesis, rRNA processing, and ribosomal large subunit biogenesis." (PMID 40406148, 2025). "C1 IGHA1+ aerobic respiration, respiratory electron transport chain, ATP synthesis linked electron transport, mitochondrial ATP synthesis coupled electron transport, oxidative phosphorylation, and other pathways were enriched in C2 IGHG1+ in myeloma cells." (PMID 40406148, 2025). "We classified 1501 plasma cells in MM into four distinct cell subsets, C1 IGHA1+ Myeloma cells, C2 IGHG1+ Myeloma cells, and C3 IGHG4+ Myeloma cells, in order to better understand the characteristics of plasma cells in MM." (PMID 40406148, 2025). "C1 IGHA1+ Myeloma cells were mainly distributed in the middle stage, namely State 2; C2 IGHG1+ Myeloma cells and C3 IGHG4+ Myeloma cells were mainly distributed in the final stage of the trajectory, that is, State3." (PMID 40406148, 2025). "The four identified cell subgroups were as follows: C0 IGLL5+ Myeloma Cells (724 cells), C1 IGHG4+ Myeloma Cells (310 cells), C2 MALAT1+ Myeloma Cells (305 cells), and C3 IGHG1+ Myeloma Cells (149 cells)." (PMID 39281682, 2024). "We discovered three distinct incoming signal patterns: Pattern 1 (involving T_NK cells and pDCs), Pattern 2 (involving C0 IGLL5+ Myeloma Cells), and Pattern 3 (involving C3 IGHG1+ Myeloma Cells)." (PMID 39281682, 2024). "Additionally, we observed three outgoing signal patterns: Pattern 1 (involving C0 IGLL5+ Myeloma Cells), Pattern 2 (involving C3 IGHG1+ Myeloma Cells), and Pattern 3 (involving T_NK cells, B cells, and pDCs)." (PMID 39281682, 2024). "The biological process with the highest correlation with C1 IGHG4+ Myeloma Cells was subunit; The biological process most associated with C2 MALAT1+ Myeloma Cells was biosynthetic; The biological process most associated with C3 IGHG1+ Myeloma Cells was electron." (PMID 39281682, 2024). "We investigated the differentiation trajectories of malignant plasma cells and identified four major myeloma subpopulations: C0 IGLC3+, C1 IGHA1+, C2 IGHG1+, and C3 IGHG4+ myeloma cells." (PMID 40406148, 2025). "C2 IGHG1+ Myeloma cells and C3 IGHG4+ Myeloma cells in M3 regulatory module had relatively high regulatory activity." (PMID 40406148, 2025). "This analysis resulted in the identification of four distinct cell subsets: C0 IGLL5+ Myeloma Cells, C1 IGHG4+ Myeloma Cells, C2 MALAT1+ Myeloma Cells, and C3 IGHG1+ Myeloma Cells." (PMID 39281682, 2024). "The results showed that C0 IGLC3+ myeloma cells had the highest differentiation potential, indicating that C0 IGLC3+ myeloma cells had the strongest proliferation ability and were naive tumor cells, followed by C1 IGHA1+ myeloma cells, C2 IGHG1+ myeloma cells, and C3 IGHG4+ myeloma cells." (PMID 40406148, 2025). "Additionally, the most activated TFs in each subgroup within the M1-M5 modules were identified as follows: MAF in the C0 IGLL5+ Myeloma Cells subgroup, LEF1 in the C1 IGHG4+ Myeloma Cells subgroup, TCF12 in the C2 MALAT1+ Myeloma Cells subgroup, and CREB5 in the C3 IGHG1+ Myeloma Cells subgroup." (PMID 39281682, 2024).